IDO1 (indoleamine 2,3-dioxygenase 1)
Diseases named in the same sentence as IDO1 in open-access papers (continued):
Sharing a sentence is not in itself a finding about the gene and the disease.
tumor (continued). "The IDO1 inhibitor epacadostat has been reported to improve the anti-tumor effect of CAR-T cells in esophageal squamous cell carcinoma." (PMID 36231064, 2022). "The mechanisms by which IDO1 and kynurenine metabolites promote tumorigenesis include the shaping of a tumor-friendly immune microenvironment and the activation of aryl hydrocarbon receptor." (PMID 35903691, 2022). "In this context, the expression of Ido-1 protects premalignant cells from immune surveillance and tumor cells from anticancer drugs." (PMID 36419183, 2022). "Specifically, we applied a logistic regression, in which the expression value of IDO1 was used as the independent variable, to calculate the probability of a sample to be a tumor." (PMID 35760783, 2022). "IDO1 is necessary for MDSCs recruitment to tumor tissues, lymph nodes, and spleens for local immunosuppressive functions, and IDO1-expressing MDSCs are a crucial cell population for immunotherapy resistance in a range of tumors." (PMID 35681736, 2022). "When we cultured mitomycin-treated wt HeLa cells (as a “bystander” tumor cell model) with activated human CD8+ T cells, T cell proliferation was arrested; by contrast, loss of IDO1 in the bystander HeLa cells restored T cell proliferation." (PMID 35245456, 2022). "Upregulation of IDO1 expression has been positively correlated with poor prognosis, tumor progression, and metastasis." (PMID 35273597, 2022). "IDO1 expression can be driven by tumor PGE2, and it has been defined as a new useful prognostic marker at early stages of the disease." (PMID 36230990, 2022). "Upon NIR‐II irradiation, CuS5 induce homogeneous ICD and release immunometabolic regulator in deep tumor tissues, which ameliorates IDO‐1 mediated immunometabolic disorder and further suppresses regulatory T cells infiltration." (PMID 36073839, 2022). "IDO1 is overexpressed in many kinds of tumor cells, which reduces the level of intracellular tryptophan and the production of a series of metabolites, thus in turn affecting the function of the immune system." (PMID 36090994, 2022). "Overexpression and activation of IDO1 in tumor and antigen-presenting cells can produce toxic tryptophan metabolites and play an important role in tumor-induced immune system tolerance and inhibition, which has become a new important therapeutic target." (PMID 36558139, 2022). "In the settings of cancer, many different types of cells express Ido-1, including tumor and stromal cells, in variable proportions." (PMID 36419183, 2022). "Here, we review the role of the immunosuppression mechanisms mediated by the IDO1 pathway in tumor growth." (PMID 35681736, 2022). "Overexpression of IDO1 by human EC cells is known to enhance tumor progression in vivo, and IDO1 inhibitors improve tumor rejection in mice models when combined with checkpoint inhibitors." (PMID 36119020, 2022). "More importantly, IDO1 has been shown to play an important role in the process of immune evasion by tumor." (PMID 35563059, 2022). "CD34 and CD146 protein expression were dramatically reduced in experimental tumor tissues from IDO1 short hairpin RNA (shRNA) treated mice." (PMID 35918736, 2022). "IDO1 inhibitors combined with radiotherapy, chemotherapy, or immunotherapy can delay tumor progression by reducing the generation of kynurenine and increasing the cytotoxicity of T cells in murine models of CRC." (PMID 35571116, 2022). "Evidence from previous studies suggests that tumours prefer to up-regulate TDO2 more than IDO1 or IDO2." (PMID 36286592, 2022). "KYN has previously been shown to bind to and activate the AHR, providing another important link to the pro-tumor effects of IDO1." (PMID 35245456, 2022). "Expression of proteins such as IDO1 and PD-L1 aligns with immune-evasion mechanisms observed in the tumor-immune ME." (PMID 35058616, 2022). "IDO1 represented indoleamine 2,3-dioxygenase 1 and was well characterized as a mediator of tumor immune evasion." (PMID 35905417, 2022).
tumor (continued). "Though IDO1 is also overexpressed by the tumor cells, what has caught the most attention is its overexpression in the DCs that depletes tryptophan in the TME leading to T-cell anergy and immune tolerance by the tumor cells." (PMID 35997090, 2022). "IDO1-activated Tregs develop and infiltrate the tumor microenvironment, suppressing local immune surveillance and promoting tumor development and metastasis." (PMID 35681736, 2022). "Several studies have shown that the IDO1-KYN-AHR axis plays a role in the induction of an immunosuppressive microenvironment in tumours; however, its role in promoting intestinal homeostasis and regulating inflammatory responses should not be ignored." (PMID 36555220, 2022). "Generally, IDO1 suppresses T-cell function through induced tryptophan starvation, leading to tumor development." (PMID 36139584, 2022). "Subsequent work in a different model revealed that inhibition of IDO1 constitutive expression in tumor cells with COX2 inhibitor celecoxib also promoted tumor immune rejection." (PMID 36188218, 2022). "Microbial invasion and tumour aggression are therefore facilitated by the expression of IDO1 and its suppression of host immune surveillance and cell destruction, coupled with suppression of the differentiation and activity of effector T cells and NK cells." (PMID 35371018, 2022). "The up-regulation of IDO1 expression is positively correlated with poor prognosis and tumor progression and metastasis." (PMID 35875026, 2022). "This was due to the ability of IDO1-expressing tumor cells to prevent their immune rejection, as both types of tumors progressed with the same kinetics in immunocompromised/irradiated mice." (PMID 36188218, 2022). "Adverse events with JAK1 inhibition combined with either IDO1 or PI3Kδ inhibition were manageable, but the combinations demonstrated limited clinical activity or enhancement of immune activation in the tumor microenvironment." (PMID 35288468, 2022). "miR-448, a tumor suppressor, attenuates the expression of IDO1 and enhances the activation of CD8+ T cells." (PMID 35909469, 2022). "Imatinib stimulated CD8+ T cells and triggered Treg death within the tumor via decreasing IDO1 expression on tumor cells." (PMID 35918736, 2022). "More importantly, innovative therapeutic strategies targeting IDO1 have attracted increasing attention, in which IDO1 inhibitors showed remarkable results in tumor development suppression." (PMID 36172162, 2022). "After confirming the pharmacokinetics/pharmacodynamics of YH29407, the anti-tumor effects of IDO1 inhibitors were evaluated." (PMID 36545214, 2022). "Regulatory T cells (Tregs; CD4+ FoxP3+ CD25+) are regulatory T cells that promote and maintain the immunosuppressive tumor microenvironment and can be activated by the immunosuppressive mediator, indoleamine 2,3 dioxygenase 1 (IDO1)." (PMID 36011015, 2022). "Here the authors report the design of an ultrasound-controlled CRISPR/Cas9 gene editing system for IDO1 silencing compounded with the probiotic Lactobacillus rhamnosus GG, showing the induction of anti-tumor immune responses in preclinical cancer models." (PMID 36550159, 2022). "In a pharmacodynamic study, YH29407 suppressed Kyn most effectively in tumor tissues, and it was shown to have improved pharmacodynamics compared to existing IDO1 inhibitors." (PMID 36545214, 2022). "Based on these findings, the administration of YH29407 twice a day led to more efficient activation of T cells and greater anti-tumor effects in comparison to the administration of currently available first- and second-generation IDO1 inhibitors." (PMID 36545214, 2022). "Given the physiological importance of the IDO1 enzyme within the tumor microenvironment, the need for structural studies and the development of increasingly efficient inhibitors has become an attractive approach to treating cancer patients." (PMID 36145319, 2022).
tumor (continued). "Despite the heterogeneity of the response between patients, the triple combination of MEK, PD-L1 and Ido-1 inhibitors exerted the strongest effect with a further 15% increase in tumour cell death over the double combination of MEK and PD-L1 inhibitors." (PMID 36419183, 2022). "ASPNhigh/ KYNUhigh fibroblasts were detected in the tumor periphery, where few cancer cells reside, and many were also IDO‐1‐positive and KMO‐positive." (PMID 34379869, 2022). "Accordingly, inhibition of IFNs production and interference with IDO1 expression will be an inspiring and promising direction in tumor therapy." (PMID 35681736, 2022). "When the NPs were combined with epacadostat, a compound tested in multiple clinical trials, that reverses IDO-1 immune suppression, this resulted in systemic immune activation and complete recovery from the tumor." (PMID 36135572, 2022). "In preclinical studies, IDO1 was shown to be involved in the tumour escape from immune surveillance and its activation in human cancers was associated with poor prognosis." (PMID 35454819, 2022). "Individual LLTC-hIDO1 tumours showed variable expression of human IDO1 in contrast to GL261-hIDO1 tumours which were homogenous in their IDO1 expression and were subsequently used for in vivo studies." (PMID 36145311, 2022). "As widely reported, Foxp3 and IDO1 are co-expressed in a series of tumor tissues, suggesting that IDO1 is involved in the differentiation of T cells into Foxp3 Tregs and promotion of tumor growth." (PMID 35681736, 2022). "On the other hand, expressions of both EV-derived ICOS and IDO1 displayed a high correlation with the content of circulating tumor marker CA72.4." (PMID 36077704, 2022). "IDO1 downregulates natural killer cell receptors, and by mechanism, tumor cells escape immune surveillance." (PMID 35187162, 2022). "Tumor cells are also capable of overcoming IDO1 inhibition by overexpressing other enzymes involved in tryptophan metabolism such as TDO and IDO2." (PMID 35159363, 2022). "We previously reported that Ido1 expression in the tumor adjacent mammary fat pad was decreased after anti-PD-1 immunotherapy in obese mice." (PMID 35775614, 2022). "Lastly, the IDO1-kynurenine AhR axis upregulates PD1 expression in CD8 T cells providing an immune tolerant microenvironment for tumor cells." (PMID 35681770, 2022). "One key mechanism is mediated through increased expression of the tryptophan-catabolising enzyme indoleamine 2, 3-dioxygenase 1 (IDO1) in the tumour." (PMID 36145311, 2022). "Since Ido-1 expression in cancer is modulated by interaction with stromal and immune cells, we extended our analysis to tumor samples interrogating the clinical dataset of TCGA NSCLC cohort." (PMID 36419183, 2022). "According to our results, YH29407, a second-generation novel IDO1 inhibitor, shows a superior anti-tumor effect compared to first-generation epacadostat and second-generation BMS-986205." (PMID 36545214, 2022). "Tumors of mice with knockdown of IDO1 in 4T1 cells exhibited significant growth inhibition compared to vector control group, suggesting that IDO1 knockdown reduced tumor burden compared to the control group." (PMID 36550159, 2022). "Previous studies revealed that inhibition of IDO1 restores T-cell activity and improves the ability to kill tumor cells." (PMID 36139584, 2022). "Indoleamine 2,3 dioxygenase 1 (IDO1) as an immune checkpoint molecule converts tryptophan to kynurenine, which is associated with tumor immunosuppression." (PMID 36110223, 2022). "Studies have shown that the up-regulation of IDO1 expression is positively correlated with poor prognosis and tumor progression and metastasis." (PMID 36059531, 2022). "In the current study, we reported a crucial role of IDO1 in DLBCL tumor growth and that IDO1 overexpression was significantly correlated with poor outcomes in DLBCL patients." (PMID 35760783, 2022).
tumor (continued). "Further, the expression level of immune checkpoint molecules (PDL1, CTLA4, LAG3, TIGIT, CD27, IDO1, ICOS) and tumor mutational burden (TMB) also showed significant differences between the two subtypes, indicating the clinical value of the two subtypes." (PMID 36568197, 2022). "IDO1 is always expressed on the surface of antigen-presenting cells, myeloid-derived suppressor cells (MDSCs), and various tumor cells, including sarcoma, breast cancer, and chronic lymphocytic leukemia." (PMID 36358792, 2022). "Silencing IDO1 gene or using molecule inhibitor of IDO1 significantly reduces the number of tumor neovascularization and inhibits the invasion and migration of cancer cells." (PMID 35681736, 2022). "Activation of IDO1 can be observed in tumour cells themselves as well as stromal and vascular cells and innate immune cells." (PMID 35454819, 2022). "IDO1 can also be induced in specific subsets of antigen-presenting cells, leading to immune tolerance to tumor antigens." (PMID 34981784, 2022). "We discuss obstacles encountered in using IDO1 as a new tumor immunotherapy target, as well as the current clinical research progress." (PMID 35681736, 2022). "The average QIF scores of PD-L1, HHLA2, B7H3, IDO-1 and Galectin-9 were significantly higher in the stromal compartment than in the tumor subregion." (PMID 35145510, 2021). "Inflammatory stimuli-mediated EMT has been shown to confer immunoregulatory properties to neoplastic epithelial cells by activation of IDO1 and enhancing tumor immune escape." (PMID 34946170, 2021). "When a cut-off of 10% stained tumor cells was used to define positive samples, 32% of cases were defined as iNOS positive, 25% as IDO1 positive, and 59% as PD-L1 positive." (PMID 33466316, 2021). "Tumor cells can overexpress Indoleamine 2,3-dioxygenase 1 (IDO1), a rate-limiting enzyme that converts tryptophan to kynurenine, leading to an immune suppression through T cell apoptosis and loss of function." (PMID 33718169, 2021). "Tumor vascular abnormalities and the immunosuppressive tumor microenvironment (TME) caused by indoleamine 2,3-dioxygenase 1 (IDO1) seriously affect the efficacy of PDT-mediated immunotherapy." (PMID 34834367, 2021). "The activated enzyme IDO1 reduces Trp levels in the tumor microenvironment, and this decrease has an intratumoral immunosuppressive effect." (PMID 33466316, 2021). "More importantly, the efficiency of ADH-1 in decreasing the tumor size and prolonging mouse survival time was better than those of anti-PD-1, anti-IDO-1 and anti-CTLA-4 when used individually or in combination." (PMID 33692219, 2021). "Tumor infiltrating lymphocytes in GBM upregulate IDO1 and greater IDO1 gene expression correlates with worse prognosis in GBM patients." (PMID 34277419, 2021). "Among several immunosuppressive mechanisms, indoleamine 2,3-dioxygenase (IDO1) has emerged as a key targetable pathway impacting the anti-tumor function of TIL." (PMID 34025677, 2021). "Harnessing the Trp-indole pathways in bacteria and the host hold the potential to attack the tumor cells through several different facets; Trp starvation, IDO1 inhibition, and indolic AhR activation." (PMID 33916690, 2021). "Accordingly, we also observed an increase in inhibitory checkpoints that can be expressed in both NK and T cells such as LAG-3 and suppressors of anti-tumor immunity such as IDO1." (PMID 34880879, 2021). "We expect future research to work on the impacts driven by IDO1 regulation, particularly on the dormancy mechanisms in addition to the active tumours." (PMID 34539663, 2021). "IDO1 is reported to modulate the tumor microenvironment, induce immune tolerance to tumors, promote immune escape, and contribute to HCC progression." (PMID 34769098, 2021). "In contrast, in the immunologically hot CT26-HER2 tumor, the checkpoint molecules and effectors, including CTLA-4 and Ido1, were at high levels; the tumor responded to checkpoint blockade." (PMID 34578328, 2021).
tumor (continued). "It potently reduces intracellular KYN levels and IDO1-induced T cell anergy, and slows tumor cell growth, both in-vitro and in-vivo, in monotherapy and combined with antibodies directed against PD-L1." (PMID 34201791, 2021). "Indoleamine 2,3 dioxygenase 1 (IDO1), which is involved in tryptophan metabolism, was associated with tumor infiltration modulation towards a tolerant response by recruiting and activating both myeloid-derived suppressive cells (MDSC) and Tregs." (PMID 34205397, 2021). "IE9mp1-mIDO1 tumor cells expressed the murine IDO1 (mIDO1) gene and the gene product demonstrated functional enzyme activity, as measured by elevated Kyn production compared to empty vector (IE9mp1-EV) controls." (PMID 34025677, 2021). "PD-L1 and IDO-1 expression was detectable in the LNCap C1 tumor sample after stimulation with IFN-γ, while PC3-derived tumors lacking N-cadherin no longer expressed PD-L1 and IDO-1." (PMID 33692219, 2021). "The molecular mechanisms for the effects of IDO‐1 overexpression point toward maintenance of immunosuppression in tumor microenvironment, due to depletion of effector T cells and enrichment of regulatory T cells." (PMID 33615152, 2021). "BMS-986205 can reverse the immunosuppression system in cancer patients by inhibiting IDO1 and decreasing the Kyn levels of tumor cells." (PMID 33883013, 2021). "In conclusion, we identified dexamethasone as a potent suppressor of tumor immune evasion, which can target PD-L1 and IDO1 simultaneously." (PMID 34175886, 2021). "In cancer, however, both ARG1 and IDO1 are overexpressed, in MDSCs and DCs, and contribute to the impairment of the host anti-tumor immunity." (PMID 34389039, 2021). "Very recently, tryptophan metabolism via the enzyme IDO1 has been proven to serve as one-carbon unit for nucleotide synthesis, substituting serine and glycine and, subsequently, supporting tumour growth in genetically engineered PDAC mouse models." (PMID 34588983, 2021). "Acting as a “brake” or “accelerator” in tumor immune regulation, IDO1 induces immunosuppressive tumor microenvironment and enables cancer cells to escape immune surveillance by catabolizing tryptophan into tryptophan." (PMID 33718227, 2021). "IDO1 can be expressed by a variety of cells in the broad tumor micro-environment e.g. tumor, endothelial and stromal cells." (PMID 34557196, 2021). "We found that IDO1 expression was associated with clinical parameters, such as a presence of risk factors for HCC and tumor stage II and III, while the expression of FASLG in CCA patients was associated with the lymph node stage." (PMID 34069452, 2021). "Identification of novel therapeutic targets includes a study on the role of IDO1 in immune evasion and tumour growth." (PMID 33541164, 2021). "Further analysis based on tumor grade classification showed grade-dependent upregulation of IDO1 in tumors (grade 1 to 3) compared to control counterparts." (PMID 34769098, 2021). "Tryptophan is a theoretical source of one-carbon units through metabolism by IDO1, an enzyme intensively investigated in the context of tumor immune evasion." (PMID 33831358, 2021). "IDO1 is a type of tryptophan catabolic enzyme which inactivates T cells and induces tumor immunotolerance." (PMID 34134781, 2021). "The overexpression of IDO1 in tumours has been suggested to be induced by the IFN-γ generated by tumour-infiltrating T-cells as an adaptive resistance mechanism." (PMID 34680327, 2021). "We herein review the current efforts on investigating the interactions between IDO1 signalling and tumour dormancy and discuss possible directions for future research on cancer therapy via targeting these interactions." (PMID 34539663, 2021). "IDO1 has been shown to induce immune suppression in the local tumor environment by promoting the differentiation of regulatory T cells and by inhibiting the function of effector T cells." (PMID 33390854, 2021).